ICAM1 (intercellular adhesion molecule 1)
Diseases named in the same sentence as ICAM1 in open-access papers (continued):
Sharing a sentence is not in itself a finding about the gene and the disease.
colorectal cancer (continued). "In our study, we found that ICAM-1 derived from MTCAFs promotes the migration and invasion of colorectal cancer cells by binding LFA-1 receptor of colon cancer, subsequently activating AKT and STAT3 in HCT116 cells." (PMID 36016615, 2022). "In summary, we found that ICAM-1 secreted from CAFs enhances the migration and invasion ability of colorectal cancer cells by activating the AKT and STAT3 pathway in cancer cells." (PMID 36016615, 2022). "ICAM-1 secreted from MTCAFs enhances the migration and invasion ability of colorectal cancer cells by activating the AKT and STAT3 pathway in cancer cells." (PMID 36016615, 2022). "Although we confirmed the important role of MTCAF-derived ICAM-1 in colorectal cancer, there are still many limitations, such as stage IV patients were not included in our study." (PMID 36016615, 2022). "Another important protein is soluble intercellular adhesion molecule-1 (sICAM-1), which is elevated in the sera of different cancers and is considered to be a prognostic marker in patients with colorectal cancer." (PMID 33918514, 2021). "Elevated levels of ICAM1 were reported in several malignancies, where increased ICAM1 expression in breast, gastric, and colorectal cancers is correlated with more favorable prognosis." (PMID 30082828, 2018). "For example, elevated serum levels of ICAM1 in colorectal cancer patients were correlated with tumor stage and tendency to metastasis formation." (PMID 28105922, 2016). "It was previously suggested that ICAM1 is regulated by miR-222 and miR-339 in colorectal cancer cells and glioma cells and by miR-221 in cholangiocytes." (PMID 26338962, 2015). "Our analysis revealed a significant upregulation in ICAM-1 mRNA expression in colorectal carcinoma tissues as compared with normal specimens." (PMID 26068788, 2015). "Our findings provide evidence of the molecular mechanisms by which SDF-1 induces ICAM-1 expression in colorectal cancer cells." (PMID 23098564, 2012). "In the present study, we show that SDF-1 induces ICAM-1 expression in colorectal cancer DLD-1 cells." (PMID 23098564, 2012). "The contribution of integrin LFA-1 to VEGF secretion via COX-2 was a micro environmental-related mechanism leading to the pro-angiogenic activation of soluble ICAM-1-activated colorectal carcinoma cells." (PMID 18844982, 2008). "Soluble ICAM-1 promotes angiogenesis and the growth of colorectal cancer." (PMID 37569878, 2023). "To explore the correlations between ICAM-1 expression and progression and prognosis of patients with colon cancer, we collected patients samples with colon cancer from Oncomine Database, which includes paracarcinoma tissue and colorectal cancer tissue." (PMID 36016615, 2022). "MTCAF-derived ICAM-1 may play an important role in promoting cancer metastasis and can serve as a predictive and prognostic biomarker in colorectal cancer." (PMID 36016615, 2022). "Changes in CDX gene expression further promoted metastasis as ICAM-1 increases cancer cell invasion/intravasation into the microvasculature and mediates peritoneal carcinomatosis HP promotes colorectal cancer cell motility and SERPINA3 promotes tumor cell migration and invasion." (PMID 34010296, 2021). "In order to provide clinical guidance for the treatment of CRC, this study is conducted to investigate the correlations of intercellular adhesion molecule 1 (ICAM-1) gene polymorphisms with susceptibility and multidrug resistance (MDR) of colorectal cancer (CRC)." (PMID 28816939, 2017). "Moreover, the transfection of ICAM-1 into colorectal cancer cell lines inhibits tumor growth and metastasis." (PMID 29099772, 2017). "ICAM-1 is a polymorphic gene, thus, the present study investigated the relationship between the polymorphisms of ICAM-1 and the susceptibility and phenotypical characteristics of colorectal cancer (CRC)." (PMID 19822019, 2009).
colorectal cancer (continued). "Indeed, ICAM-1 is up-regulated in CAF associated with colorectal cancer, but no information was so far available on possible functional consequences." (PMID 27901489, 2017). "F. nucleatum can also induce alpha-kinase 1 (ALPK1) to stimulate the NF-κB pathway, leading to the upregulation of intercellular adhesion molecule 1 (ICAM1) and metastasis of colorectal cancer (CRC)." (PMID 39456558, 2024). "Another study showed that colorectal cancer cells promote the polarization of macrophages to the M2 phenotype characterised by surface marker CD163, mediated by CCL2 and ICAM1." (PMID 37108548, 2023). "The Oncomine analysis showed that α-SMA, ICAM-1, and LFA-1 exhibited a higher expression in colorectal cancer compared with colon tissue, and ICAM-1 was positively correlated with α-SMA and LFA-1." (PMID 36016615, 2022). "In human patients, high expression of ICAM-1, VCAM-1, and MAdCAM-1 has been shown to correlate with higher density of CD8+ T cells in colorectal cancer (CRC) tumors and also with prolonged disease-free survival." (PMID 31231358, 2019). "Colorectal cancer cell adhesion to endothelium is a key event in tumor progression; CXCL12/SDF-1α treatment stimulates intercellular adhesion molecule-1 (ICAM-1) expression, thus promoting tumor cell adhesion." (PMID 24971349, 2014). "Recent studies have indicated that the serum ICAM-1 and/or VCAM-1 are increased in HCC, breast and colorectal cancer." (PMID 24555415, 2014). "In breast, gastric, and colorectal cancers, increased ICAM-1 expression in cancer cells was correlated with a more-favorable prognosis, suggesting a role of ICAM-1 in enhancement of immune surveillance." (PMID 24069166, 2013). "Serum concentrations of ICAM-1 and VCAM-1 were significantly elevated in the patients with colorectal cancer in comparison with a group of healthy subjects (P < 0.00001)." (PMID 9667659, 1998). "Earlier studies reported that carnosine inhibits cancer cell adhesion, migration, invasion, and proliferation in human colorectal cancer (HCT-116) (integrin β1) and ovarian cancer cells, while it also reduces ICAM-1 and E-selectin levels in umbilical vein cells (EA.hy926)." (PMID 41008974, 2025). "Similar findings were observed in colorectal cancer patients, where neutrophils enhanced TCR signaling in CD8+ T cells, in a cell-to-cell contact dependent manner through the interaction between CD54/intercellular adhesion molecule 1 (ICAM-1) expressed on neutrophils and CD11a expressed on T cells." (PMID 38426089, 2024). "Another recent study on colorectal cancer metastasis found that F. nucleatum induced a novel pattern recognition receptor, ALPK1, to activate the NF-κB pathway, gave rise to upregulation of ICAM1, which in turn enhanced the adhesion of colorectal cancer cells to endothelial cells." (PMID 37148441, 2023). "Curcumin has been found to suppress TGF-β expression, such as p-SMAD2, TGF-β3, MMP-13, and NF-κB tumor-promoting factors as well as metastatic active adhesion molecules, such as intercellular adhesion molecule 1 (ICAM-1) and β1-integrin in stromal fibroblasts and colorectal cancer cells." (PMID 33228222, 2020). "Evaluating ICAM-1 expression in a pancreatic islet cell carcinoma (RIP1-Tag5 model), a colorectal cancer model (CT26) and B16-OVA tumors showed that extravasation of CD8+ T cells was E-selectin, P-selectin and ICAM-1 dependent, which could be blocked using corresponding blocking antibodies." (PMID 33262763, 2020). "Indeed, an increase in TILs was observed in ICAM-1 positive gastric and colorectal cancers compared to ICAM-1 negative tumors." (PMID 31231358, 2019). "However, the function of ICAM-1 in CAFs has not been revealed in the TME of colorectal cancer." (PMID 36016615, 2022). "However, it is not clear whether the regulation of ICAM-1 expression and cell adhesion are mediated by SDF-1 in colorectal cancer cells." (PMID 23098564, 2012).
diabetic retinopathy (57 papers, 2009 to 2025). "The ICAM-1 signaling pathway is activated in diabetic retinopathy, and increased levels of ICAM-1 are associated with the severity of DR." (PMID 40864768, 2025). "At circulating protein levels, genetically predicted a higher level of ICAM1 (OR 1.05, 95%CI 1.03–1.08) was positively connected with the risk of diabetic retinopathy." (PMID 39199149, 2024). "Deletion of CD40 in diabetic mice decreased inflammatory responses linked to the pathogenesis of diabetic retinopathy, such as retinal leukostasis, capillary degeneration, ICAM-1 upregulation and protein nitration." (PMID 37958563, 2023). "And increased levels of serum vascular endothelial growth factor and intercellular adhesion molecule-1 levels in diabetic retinopathy are associated with an increase in the severity of diabetic retinopathy and ellipsoid zone disruption." (PMID 34526548, 2021). "ICAM1 has already been identified as playing a key role in diabetic retinopathy and vascular inflammation, and the knockdown of ICAM1 can reduce endothelial injury and the loss of pericytes." (PMID 33115500, 2020). "Genetic studies have reported contradictory results on the association between the intercellular adhesion molecule-1 (ICAM-1) rs5498 polymorphism and diabetic retinopathy (DR) risk in type 2 diabetic patients." (PMID 30419874, 2018). "CD18, a leukocyte cell surface adhesion molecule that binds with ICAM-1 implicated in the pathogenesis of diabetic retinopathy, was assessed by flow cytometry using an antibody-based fluorescence assay." (PMID 27509144, 2016). "The rs5498-ICAM-1 polymorphism was reported to be associated with an increased expression of ICAM-1 in our study in which subjects with T2DM with diabetic retinopathy were enrolled." (PMID 27090396, 2016). "ICAM-1 has been implicated in the development of leukostasis, a prominent feature of diabetic retinopathy." (PMID 23922493, 2013). "An increase in serum VEGF and ICAM-1 levels is associated with an increase in the severity of diabetic retinopathy and the grade of ELM and IS-OS junction disruption." (PMID 23922493, 2013). "We have investigated the possibility of using a single short synthetic duplex RNA to suppress the expression of VEGF-A and ICAM-1; genes implicated in the progression of ocular neovascular diseases such as diabetic retinopathy." (PMID 19531249, 2009). "In addition, the serum levels of ICAM-1 had been also confirmed to be associated with increased severity of diabetic retinopathy." (PMID 33256661, 2020). "In accordance to our study, a meta‐analysis showed that the K469E polymorphism in the ICAM‐1 gene may increase individuals' susceptibility to diabetic microvascular complications, including diabetic nephropathy and diabetic retinopathy." (PMID 31157518, 2019). "Our previous studies highlighted that enhanced oxidative stress, and increased serum VEGF and ICAM-1 levels are associated with an increase in the severity of diabetic retinopathy resulting in an increase in macular thickness and increased grades of RPE alterations." (PMID 31700679, 2019). "Patients with diabetic retinopathy exhibit elevated serum levels of irisin and intercellular adhesion molecule-1 (ICAM-1) in the early stages of the disease, with levels decreasing in later stages." (PMID 41302503, 2025). "Another study reported upregulation of CD40, TRAF2, and TRAF6 in patients with diabetic retinopathy, where CD40 was associated with the expression of pro-inflammatory molecules such as intercellular adhesion molecule 1 (CD54), CCL2, and TNFα." (PMID 38554187, 2024). "ICAM-1 upregulation in retinal endothelial cells and leucostasis are important features of diabetic retinopathy." (PMID 35920844, 2022). "Experiments using a rat model of streptozotocin-induced diabetic retinopathy showed that H2S treatment attenuated the increased expression of IL-1ß, ICAM-1, iNOS, and COX-2." (PMID 35628328, 2022).
diabetic retinopathy (continued). "With the progression of diabetic complications, such as diabetic nephropathy, diabetic peripheral neuropathy, and diabetic retinopathy, the level of ICAM1 further increases." (PMID 35046894, 2021). "Advanced glycation end-products or glycation proteins can induce the release of pathophysiological substances such as IL-6, IL-8, MCP-1, ICAM-1, and IP-10 in conditions such as diabetic retinopathy." (PMID 34871313, 2021). "Diabetes retinopathy patients in a meta-analysis research showed that ICAM-1 expression was related to the severity of diabetes retinopathy and generally exists in patients." (PMID 33255669, 2020). "Our results are also consistent with the pathology of diabetes retinopathy, showing a decrease of tight junction-related protein expression and increased ICAM-1 in the high glucose- and 4-HNE-induced retinopathy." (PMID 33255669, 2020). "Analyses by western blot and flow cytometry indicate that pro-inflammatory molecules known to be associated with the pathogenesis of diabetic retinopathy were significantly elevated following high glucose exposure, including VEGF, ICAM-1, and ROS." (PMID 30846806, 2019). "In our previous study, increase in serum levels of VEGF and ICAM-1 with increase in severity of diabetic retinopathy was documented." (PMID 27847626, 2016). "ICAM-1-mediated leukostasis has been identified as an early pathological event in the mouse model of diabetic retinopathy." (PMID 26920853, 2016). "The results in the present study indicated that ATWLPPR had retinal protective effects against vascular injury, oxidative stress and up-regulation of GFAP, VEGF and ICAM-1 in a mouse model of the early stages of experimental diabetic retinopathy." (PMID 26554379, 2015). "This study evaluated the status of serum VEGF and ICAM-1 levels and their association with ELM and photoreceptor IS-OS junction disruption in different stages of diabetic retinopathy." (PMID 23922493, 2013). "Several studies have documented an increase in expression of ICAM-1 in animal models of diabetic nephropathy and diabetic retinopathy." (PMID 23922864, 2013). "Furthermore, the upregulation of the protein Icam 1 is particularly essential for the migration of leukocytes and has been described in several ocular diseases, such as diabetic retinopathy and CNV." (PMID 38247855, 2024). "Interestingly, CD40 promotes ICAM-1 upregulation, leukostasis, and retinal capillary degeneration, and is required for the development of diabetic retinopathy." (PMID 38474393, 2024). "Immunological mechanism studies show that the up-regulation of ICAM1 and other inflammatory factors in the retina of diabetic retinopathy patients may be related to the pathway mediated by CD40 and its ligands." (PMID 39199149, 2024). "In this same study, administration of DHTS prior to exposure to high glucose and BzATP prevented overexpression of both P2X7R and VEGF-A, with a strongest effect on the latter, as well as of ROS and other factors involved in the pathogenesis of diabetic retinopathy, such as ICAM-1." (PMID 34281162, 2021). "Since ICAM-1 is the primary adhesion molecule involved in the pathogenesis of diabetic retinopathy (DR), the elevated level of ICAM-1 may facilitate the recruitment of leukocytes into the damaged retina." (PMID 32194402, 2020). "In addition, NF-κB is known to bind to the promoters and increase the transcription of the adhesion molecule ICAM-1 and the chemokines MCP-1 and FKN, all of which are associated with inflammation in diabetic retinopathy." (PMID 26765843, 2016). "ICAM-1 is one of the most recognizable initiators of leukocyte-endothelial cell adhesion and has been highly correlated with ocular inflammatory disorders such as diabetic retinopathy, retinopathy of prematurity, and RR)." (PMID 24956278, 2014).
diabetic retinopathy (continued). "In this study, we used bone marrow chimeric mice to investigate the tissue sources and role of NOX2 in ROS generation, upregulation of VEGF and ICAM-1 expression and two early indicators of diabetic retinopathy, leukostasis and breakdown of the blood retinal barrier." (PMID 24358357, 2013). "A number of studies evaluated the association of intracellular adhesion molecule-1 (ICAM-1) K469E (rs5498, A/G) gene polymorphism with diabetic microvascular complications (DMI) including diabetic nephropathy (DN) and diabetic retinopathy (DR) in different populations." (PMID 23922864, 2013). "Increased ICAM-1 concentration in diabetic retinopathy has also been previously reported." (PMID 23922493, 2013). "First, previous studies have demonstrated that the expression of both retinal VEGF mRNA and ICAM-1 were upregulated in rodent models of diabetic retinopathy and ICAM-1 levels were decreased by suppressing VEGF activity associated with a decrease in BRB breakdown and leukostasis." (PMID 21139695, 2010). "Downregulation of the expression of VEGF and ICAM-1 could protect against diabetic retinopathy." (PMID 40864768, 2025). "As CD40-driven ICAM-1 expression and CCL2 production are essential for the pathogenesis of inflammatory diseases, including diabetic retinopathy, advanced glycation end products-mediated CD40 dysregulation is functionally relevant." (PMID 40005847, 2025). "AGE-mediated CD40 upregulation was functionally relevant since it enhanced CD40-driven expression of ICAM-1 and production of CCL2, events central to the pathogenesis of inflammatory disorders, including diabetic retinopathy." (PMID 38474393, 2024). "In summary, soluble secreted proteins of tears such as inhibition of ICAM-1 and TNF-α exert valuable effects on the prevention of early diabetic retinopathy." (PMID 39279894, 2024). "Sesamin administration reduced levels of tumor necrosis factor-α (TNF-α) and intercellular adhesion molecule-1 (ICAM-1) and suppressed inducible nitric oxide synthase (iNOS) expression in a mouse model of diabetic retinopathy." (PMID 38337729, 2024). "The main symptom of diabetic retinopathy is the leakage of blood from the loosened blood vessels and related with COX2, ICAM‐1, and VEGF." (PMID 35092362, 2022). "It has been shown that the expression of NF-κB p65 in the retina can regulate the expression of intercellular adhesion molecule-1 (ICAM-1), which is the primary adhesion molecule responsible for inflammation in the pathogenesis of diabetic retinopathy." (PMID 29682153, 2018). "ICAM-1 and VCAM-1 mediate leukocyte adhesion to the retinal vasculature, that induces capillary occlusion which has a critical role in the development of diabetic retinopathy (DR)." (PMID 25287126, 2014). "Also detectible in the early stages of diabetic retinopathy in both diabetic animals and patients is an increase in the number of leukocytes adhering to retinal blood vessels (leukostasis), and an increase in the expression of retinal intercellular adhesion molecule-1 (ICAM1, CD54)." (PMID 24205223, 2013). "Early signs of vascular injury during diabetic retinopathy include increased production of VEGF, up regulation of intracellular adhesion molecule-1 ICAM-1." (PMID 24358357, 2013). "In diabetic rats, curcumin significantly reduced TNF-α levels in the retina, prevented experimental diabetic retinopathy, decreased MCP-1 and ICAM-1 levels in the kidney, and ameliorated macrophage infiltration." (PMID 23285282, 2012). "Subsequently, a decoy peptide based on the sequence of the HR was used as a prorenin blocker and was found to have a beneficial, inhibitory effect on diabetic retinopathy by mitigating the production of vascular endothelial growth factor (VEGF) and intercellular adhesion molecule-1 (ICAM-1)." (PMID 35041699, 2022).